PIK3CB (phosphatidylinositol-4,5-bisphosphate 3-kinase catalytic subunit beta)
Diseases named in the same sentence as PIK3CB in open-access papers (continued):
Sharing a sentence is not in itself a finding about the gene and the disease.
ovarian carcinoma (7 papers, 2013 to 2024). A malignant neoplasm originating from the surface ovarian epithelium. "miR-337-3p directly targets PIK3CA and PIK3CB, suppresses the proliferation of epithelial ovarian cancer cells and reverses resistance." (PMID 38539161, 2024). "The second most copy number gains were seen in PIK3CB (27%) and Cyclin-D2 (27%), which would account for uncontrolled cell cycle progression in ovarian cancer." (PMID 23591839, 2013). "MiR-337-3p is a tumor inhibitor in several human cancers; it reduced ovarian cancer cell growth by regulating PIK3CA and PIK3CB." (PMID 33896365, 2021).
lung carcinoma (6 papers, 2018 to 2023). "Various positions were observed to be mutated in the PIK3CB gene, including lung carcinoma, thyroid cancer, and lymphoma." (PMID 36539659, 2022). "Here, we found that Gsk3b, Notch2, Pik3cb, Myc, Cdkn1a, and Smad3 were increased in human lung cancer tissue and Cd‐transformed cells, while Pik3cb, Myc, Cdkn1a, and Smad3 were negatively correlated with circCIMT." (PMID 36814305, 2023). "PIK3CA is the most studied among PIK3 mutations, with amplification or clustering of somatic mutations occurring in up to 30% of endometrial, breast, ovarian, and colon cancers while PIK3CB is found in thyroid and lung cancers." (PMID 33619913, 2021). "Furthermore, we found increased mRNA of PIK3CB, PIK3CD, PIK3CG, BCL2, TUBB3 in ALK-positive lung cancer, which suggested activation of PI3K/AKT signaling pathway." (PMID 34234236, 2021).
gastric cancer (5 papers, 2019 to 2026). A primary or metastatic malignant neoplasm involving the stomach. "VGLL1 expression was positively correlated with PIK3CA and PIK3CB, which are associated with poor OS in gastric cancer patients." (PMID 31816819, 2019). "The four prioritized mutations (PTPRK, PIK3CB, LRP1B, and IGF2R) provide new insights into the genetic landscape of gastric cancer and represent promising candidates for the development of targeted therapeutic strategies." (PMID 41696640, 2026). "In this study, we discovered VGLL1 as a novel prognostic biomarker correlated with PIK3CA or PIK3CB in gastric cancer." (PMID 31816819, 2019). "VGLL1 is a prognostic biomarker that correlates with PIK3CA and PIK3CB in gastric cancer." (PMID 31816819, 2019). "Researches demonstrated that PIK3CA, PIK3CB, AKT1 and mTOR are overexpressed in GC cell lines, and mTOR pathway is active in almost 60% of gastric cancer patients." (PMID 30754640, 2019). "However, the regulation pattern and function of PIK3CB in gastric cancer (GC) are still unclear." (PMID 38356702, 2024). "In summary, our findings demonstrated that PIK3CB and SP1 were co-overexpressed in gastric cancer." (PMID 38356702, 2024).
Insulin resistance (5 papers, 2019 to 2024). Increased resistance towards insulin, that is, diminished effectiveness of insulin in reducing blood glucose levels. "PIK3CB has been associated with insulin resistance and hepatic glucose production according to promoter variants." (PMID 38396891, 2024). "Male CO and OC offspring displayed signs of hepatic insulin resistance, through lower mRNA expression of PIK3CB across the post-weaning lifespan." (PMID 31300679, 2019). "The regulatory role of PIK3R2 was reported as ameliorating insulin sensitivity in PIK3R2 knockout mice, while a promoter variant of PIK3CB is reported to provide protection from insulin resistance in obese and non-obese individuals." (PMID 33669862, 2021). "Males displayed insulin resistance, through slower glucose clearance despite normal circulating insulin and lower mRNA expression of PIK3R1 and PIK3CB in gonadal fat and liver respectively." (PMID 31300679, 2019).
pancreatic cancer (5 papers, 2019 to 2024). "In pancreatic cancer, it was reported that the missense variant rs142933486 in the 20th exon of PIK3CB was clearly correlated with the clinical outcome." (PMID 34239358, 2021). "PIK3CB plays a critical role in the progression of esophageal cancer cells and the metastasis of pancreatic cancer cells." (PMID 38028209, 2023). "Functionally, upregulation of PIK3CB potentiates the proliferation and migration of PTEN-deficient pancreatic cancer cells by targeting the AKT signaling pathway." (PMID 34239358, 2021). "PIK3CB overexpression has been described in pancreatic cancer and colorectal cancer 27-29." (PMID 38356702, 2024). "Interestingly, YTHDF2 predominantly binds to PIK3CB [G] compared to PIK3CB [T] in pancreatic cancer cells." (PMID 34239358, 2021). "Conversely, another study showed that the rs142933486 G>T polymorphism in PIK3CB improves PIK3CB mRNA and protein levels by derailing m6A-YTHDF2-dependent degradation mechanisms, which is significantly associated with the poor prognosis of PTEN-deficient pancreatic cancer patients." (PMID 36999016, 2023). "Oncogenic KRASG12D signals through PIK3CA, but not PIK3CB, to induce acinar-to-ductal metaplasia that is required for pancreatic tumor formation, and the catalytic activity of PIK3CA is required for this tumorigenic process." (PMID 31112530, 2019).
colorectal cancer (4 papers, 2015 to 2024). A primary or metastatic malignant neoplasm that affects the colon or rectum. "Overexpression of PIK3CB was found in patients with colorectal carcinoma, non-small cell lung cancer." (PMID 32986377, 2020). "However, suggestive significance was found between PIK3CB and colorectal cancer on the left side (p = 0.0007), androgen receptor (AR) and female gender (p = 0.0002), TGM7 and young patient (p = 0.002), and EXT1 and late stage." (PMID 34207827, 2021).
endometrial carcinoma (4 papers, 2012 to 2025). A malignant tumor arising from the epithelium that lines the cavity of the uterine body. "So far, only two studies have reported the occurrence of PIK3CB mutations in endometrial cancer, D1067V and A1048V within the kinase domain, and shown that they are oncogenic." (PMID 30544563, 2018). "Much of the research and clinical efforts have focused on PIK3CA/p110α but are starting to include PIK3CB/p110β in light of its association with loss of PTEN, the most frequent genetic alteration in endometrial carcinomas." (PMID 30544563, 2018). "The frequency of PIK3CB mutation is lower compared to the PIK3CA gene, with reported frequencies of 2% (COSMIC), 10% (TCGA-UCEC, release 13) and 8% (TCGA endometrial cancer genomic data)." (PMID 30544563, 2018). "Taken together, our findings suggest that PIK3CB/p110β contributes to some of the pleiotropic functions of PI3K in endometrial cancer, particularly in the early steps by contributing to cell proliferation." (PMID 28002804, 2017). "We also analyzed the mRNA levels of PIK3CB compared to PIK3CA in a cohort of endometrial cancer patients, including 18 with complex atypical hyperplasia (CAH), 174 primary tumors and 42 metastatic lesions." (PMID 28002804, 2017). "Consequently, mutation rates for PIK3CA are at least 10-fold higher than PIK3CB/PIK3CD/PIK3CG in solid tumours such as breast and endometrial cancer (TCGA Research Network)." (PMID 40360883, 2025). "Considering the importance of PIK3CB/p110β in PTEN-deficient tumours and the high frequency of PTEN mutations in endometrial cancer, the effect of p110β selective inhibition was evaluated in endometrial cancer cell lines, with or without PTEN loss." (PMID 30544563, 2018).
glioma (4 papers, 2022 to 2024). A benign or malignant brain and spinal cord tumor that arises from glial cells (astrocytes, oligodendrocytes, ependymal cells). "Another gene that was found to be overexpressed in high-grade gliomas (G3/G4) compared to G2 was the PIK3CB gene, which encodes the phosphatidylinositol beta-kinase-3 catalytic subunit." (PMID 38254732, 2024). "PIK3CB has been reported to be associated with a high recurrence rate of gliomas and also increases the risk of developing gliomas, resulting in decreased survival." (PMID 36065261, 2022). "Likewise, subsequent in vitro experiment on human glioma cell lines demonstrated that inhibition of PIK3CB by AZD6482 induced apoptosis and cell cycle arrest, as detected using flow cytometry with propidium iodide staining." (PMID 35096262, 2022).
melanoma (4 papers, 2020 to 2025). A malignant, usually aggressive tumor composed of atypical, neoplastic melanocytes. "Melanoma driven by V600K mutations is thought to have unique features compared to V600E, including decreased reliance on MAPK/ERK pathway over activation, increased expression of c-KIT, and upregulation of the PIK3CB-AKT anti-apoptotic pathway." (PMID 35954441, 2022). "This Pik3cb mutant had little-to-no impact upon disease trajectory, with naevus onset and melanoma initiation similar to BRAF PTEN controls, although Pik3cb mutation did seem to result in improved overall survival." (PMID 39636745, 2025).
COVID-19 (3 papers, 2021 to 2022). A disease caused by infection with severe acute respiratory syndrome coronavirus 2. "Interestingly, expression of CYTOR was significantly increased in severe COVID-19 patient group G1 (p < 0.001) and correlated with both PIK3CB (r = 0.53, p < 0.001) and VIM (r = 0.55, p < 0.001)." (PMID 33441124, 2021). "For example, we identify CYTOR, a lncRNA associated with granulocyte survival strongly upregulated in COVID-19 patient group G1, which was accompanied by strong induction of CYTOR interactors such as VIM and PIK3CB." (PMID 33441124, 2021).
diabetes (3 papers, 2021 to 2023). "As a result, IRS-related signaling by IGF1R, which is directly related to diabetes, was derived (IRS2, IGF1R, PIK3CD, and PIK3CB)." (PMID 37608331, 2023).
hepatocellular carcinoma (3 papers, 2023 to 2025). A malignant tumor that arises from hepatocytes. "For those of normal weight, the hepatitis B pathway, composed of RB1, EP300, PIK3CB, HSPG2 and JAK1 (K = 9), may serve as a key point for effective treatment and prevention, because chronic infection with hepatitis viruses is a major causative factor for hepatocellular carcinoma." (PMID 40768543, 2025).
metastatic tumors (3 papers, 2017 to 2020). "PIK3CB mRNA levels were significantly increased from precursor lesions with CAH to grade 1 EEC lesions and remained constant in higher grades, NEEC and metastatic tumors." (PMID 28002804, 2017).
non-small cell lung carcinoma (3 papers, 2020 to 2024). A group of at least three distinct histological types of lung cancer, including non-small cell squamous cell carcinoma, adenocarcinoma, and large cell carcinoma. "The hsa_circ_0084003 was upregulated in non-small cell lung cancer and was a miR-381-3p sponge to block its inhibitory effects on C–X–C motif chemokine receptor 4, thus promoting tumor cell immune evasion, and promoted pancreatic ductal adenocarcinoma progression by targeting miR-532-3p/PIK3CB." (PMID 37993879, 2023).
Obesity (3 papers, 2019 to 2025). Accumulation of substantial excess body fat. "The intersection of the results from these two plugins revealed that PIK3R1, PIK3CB, SRC, PIK3CA and PIK3 CD are core targets for the combined treatment of obesity via Crataegus pinnatifida andgut microbiota." (PMID 41032481, 2025). "In the present study, network pharmacology results showed that Crataegus pinnatifida combined with the obesity-related gut microbiota may treat obesity by targeting PIK3R1, PIK3CB, SRC, PIK3CA, PIK3 CD." (PMID 41032481, 2025). "Through network pharmacology analysis, we revealed that SMs of Crataegus pinnatifida and obesity-related gut microbiota could target obesity by interacting with PIK3R1, PIK3CB, SRC, PIK3CA and PIK3 CD." (PMID 41032481, 2025). "At 4 weeks, PIK3CB and AKT2 mRNA expression was higher by 47% and 23% respectively in perirenal adipose tissue of male offspring exposed to maternal obesity during pregnancy compared to offspring exposed to a control diet (P < 0.05)." (PMID 31300679, 2019).
renal cell carcinoma (3 papers, 2019 to 2024). "PPI networks were also analyzed for the genes involved in the ‘Renal cell carcinoma pathway,’ and several hub genes, such as PIK3CA, VEGFA, and PIK3CB were noted." (PMID 31443717, 2019). "Hub genes in the ‘Renal cell carcinoma pathway’ based on PPI analysis, such as PIK3CA, VEGFA, and PIK3CB, were noted and have also been observed to play vital roles in ccRCC." (PMID 31443717, 2019).
Sepsis (3 papers, 2019 to 2026). Sepsis is defined as life-threatening organ dysfunction caused by a dysregulated host response to infection. "Machine learning-based feature selection identified four robust biomarkers (APEX1, CTSD, SLC40A1, PIK3CB) associated with sepsis." (PMID 41041634, 2025). "A nomogram was constructed based on the expression profiles of APEX1, CTSD, SLC40A1, and PIK3CB, allowing for individualized prediction of sepsis risk." (PMID 41041634, 2025). "Molecular docking analysis further indicated potential interactions between α-HB and key targets (APEX1, CTSD, SLC40A1, PIK3CB), providing insights into the molecular mechanisms of α-HB in sepsis." (PMID 41041634, 2025). "Notably, APEX1, CTSD, SLC40A1, and PIK3CB were consistently selected by all three algorithms, underscoring their potential as robust marker genes for sepsis diagnosis and progression." (PMID 41041634, 2025). "FOXO1, KLHL3, and PCBP1 were weakly expressed in the sepsis group whereas MTF1, TMEM59, PIK3CB, and S100A9 were highly expressed in the sepsis group." (PMID 41542228, 2026). "Violin plots depict the differential expression of CTSD, SLC40A1, PIK3CB (upregulated), and APEX1 (downregulated) in sepsis patients compared to the control group (***p < 0.001)." (PMID 41041634, 2025). "qPCR results showed that the expression of S100A9, PCBP1, PIK3CB, FOXO1, and TMEM59 was consistent with the public dataset, among which S100A9, PIK3CB, and TMEM59 were significantly overexpressed in sepsis, whereas PCBP1 and FOXO1 were significantly underexpressed in sepsis." (PMID 41542228, 2026). "We speculated that GAPDH, MAPK8, PIK3CB, and MMP9 may play important roles in the ARDS-specific neutrophil phenotype distinct from sepsis." (PMID 31531373, 2019).
bladder urothelial carcinoma (2 papers, 2019 to 2023). "In a recently published study, the authors achieved PI3Kβ depletion by intra-tumoral injection of PIK3CB siRNA, which induced apoptosis and triggered regression of PTEN-mutant tumors even more efficiently than PI3Kβ inhibition in urothelial bladder carcinoma." (PMID 30709367, 2019).
epidermoid carcinoma (2 papers, 2023 to 2024).
gastric adenocarcinoma (2 papers, 2023 to 2024). "The expression of hsa-mir-125b-2 decreases cell viability and colony formation, promotes apoptosis and inhibits the migration and invasion of gastric adenocarcinoma cells, in addition to targeting the downregulation of PIK3CB expression." (PMID 37735667, 2023).
Hypertension (2 papers, 2024 to 2025). The presence of chronic increased pressure in the systemic arterial system. "Network pharmacology identified ten key bioactive compounds (e.g., liquiritigenin, isoliquiritigenin, and caffeic acid), 149 hypertension-related targets, and ten core targets such as SRC, PIK3CA, PIK3CB, EGFR, and IGF1R." (PMID 41155608, 2025).
medulloblastoma (2 papers, 2010 to 2015). A malignant, invasive embryonal neoplasm arising from the cerebellum. "However, mRNA transcripts for components of the PI-3 kinase enzyme complex, Pik3r3 and Pik3cb, and downstream targets of PI-3 kinase signaling, Mapk8 (Jnk) and Frap1 were up regulated 2.8, 1.9, 1.5, and 1.2-fold, respectively in Pten deficient medulloblastomas." (PMID 20520772, 2010). "This hypothesis was also confirmed by the observation that PIK3CA was over-expressed in primary medulloblastoma, compared to normal cerebellum, which was not the case for PIK3CB or PIK3CD." (PMID 25915540, 2015).
pancreatic ductal adenocarcinoma (2 papers, 2023 to 2025). An infiltrating adenocarcinoma that arises from the epithelial cells of the pancreas. "Moreover, METTL13/METTL14/WTAP complexes and YTHDF2 facilitate PIK3CB mRNA and protein expression levels, significantly promoting the proliferation and migration of PTEN-deficient pancreatic ductal adenocarcinoma cells." (PMID 39806412, 2025).
preeclampsia (2 papers, 2012 to 2024). Preeclampsia is a hypertensive disorder of pregnancy that is characterized by new-onset hypertension with proteinuria presenting after 20 weeks of gestation, and depending on mild or severe forms may initially present with severe headache, visual disturbances, and hyperreflexia. "Binary logistic regression analysis suggests that PIK3CB and CXCR6 have good diagnostic value for preeclampsia." (PMID 39148025, 2024). "PCR experiment results indicate an increase in the expression levels of CXCR6, PIK3CB, and OSMR at the RNA level in both subtypes of preeclampsia." (PMID 39148025, 2024). "This study, through the analysis of a placental dataset, identified inflammation-related genes such as CXCR6, PIK3CB, IL1RAP, and OSMR coexisting in early-onset and full-term preeclampsia." (PMID 39148025, 2024). "This study identified four immune-related genes, namely CXCR6, PIK3CB, and OSMR, whose roles in the pathogenesis of preeclampsia have not been fully elucidated." (PMID 39148025, 2024).
prostate tumor (2 papers, 2020 to 2021). "Although less common, PIK3CB mutation and amplification have also been detected in clinical prostate tumor specimens (0.6–1.8% and 1.8–3.1% respectively), and activation of p110β (encoded by PIK3CB) predisposes prostate intra-epithelial neoplasia in mice." (PMID 32630372, 2020). "This is due to a study of Pten loss-induced prostate tumor formation in mice, showing that the genetic deletion of Pik3cb encoding p110β isoform, but not deletion of Pik3ca, inhibits tumorigenesis together with reduction of Akt phosphorylation." (PMID 34681745, 2021).
renal carcinoma (2 papers, 2017 to 2019). A carcinoma arising from the epithelium of the renal parenchyma or the renal pelvis. "Some of these genes belong to pathways known to be dysregulated in renal cancer (e.g., ITGAV, TIAM1, and PIK3CB)." (PMID 30942869, 2019).
toxoplasmosis (2 papers, 2014 to 2019). A parasitic disease contracted by the ingestion or fetal transmission of toxoplasma gondii.
viral infections (2 papers, 2022 to 2024). "The JAK2 and IL6/JAK2/STAT3 signaling pathways are therapeutic targets for treating excessive inflammatory response to virus infection, where PIK3CB, the target of miRNA−34a participated in TCR−mediated NF−κB signaling after binding to B7 ligand on antigen presenting cells (APC)." (PMID 36298658, 2022). "The results showed that SKIV2L2, JAK2, PIK3CB, and MAPK8 were related to virus infection." (PMID 36298658, 2022). "Our analysis specifically indicates the involvement of CXCR6, PIK3CB, and OSMR in the regulation of the RIG-I-like receptor signaling pathway, a common immune signaling pathway crucial for innate immunity, inflammation, and the upregulation of antiviral proteins to control viral infections." (PMID 39148025, 2024).